MMP2 (matrix metallopeptidase 2)
Diseases named in the same sentence as MMP2 in open-access papers (continued):
Sharing a sentence is not in itself a finding about the gene and the disease.
infection (continued). "Both rs243866 and rs2285053 mutant alleles reduce the transcription activity of MMP2, which in turn modulate the ECM-remodeling and immune responses, and thus the susceptibility to infection." (PMID 31474955, 2019). "MMP-2 secretion was also dependent on the autophagy pathway activation, since when infection experiments were performed in the presence of bafilomycin A1 or chloroquine, MMP-2 secretion was partially inhibited." (PMID 30564561, 2018). "Elastase B appeared to be the predominant factor responsible for activation of MMP-2, involved in tissue destruction and establishment of infection." (PMID 29467483, 2018). "Subsequently in vitro study, similar with our previous study in vivo, we found that P1 infection downregulated the mRNA expression of mmp2 and protein expression of β-catenin in vitro." (PMID 29593670, 2018). "Infection increased placental expression of the pro-enzyme and activated enzyme form of MMP-2 and MMP-9, thus exposing both the placenta and the amniotic membranes surrounding the fetus and placenta to degradation." (PMID 29176767, 2017). "The present study successfully infected HCE cells with HSV-1 in vitro and detected MMP-2 mRNA and protein expression levels at the early stages of infection." (PMID 24348806, 2014). "Robust changes in expression of several genes was evident 7 days post-infection; expression of Col1a1, Col1a2, Col3a1, Mmp2, Mmp9 and Lox was significantly increased while expression of Timp3 was significantly decreased." (PMID 24950301, 2014). "Matrix metalloproteinase 2 (MMP2) transcript accumulated rapidly following infection with oomycete pathogen Phytophthora sojae or the bacterial pathogen Pseudomonas syringae pv." (PMID 24454805, 2014). "Matrix metalloproteinase (MMP) 9 and MMP2 were increased in WT oviducts compared to IL-17-/- animals at day 7 post-infection." (PMID 24073293, 2013). "The matrix metalloprotease MMP2 is upregulated after infection in the resistant line 63, similar to the previously observed increase at the neoplastic stage of MD." (PMID 23072359, 2012). "TSP1, also binds to matrix metalloproteinase-2(MMP-2) and appears to be involved in the infection process." (PMID 23133440, 2012). "Infection of mice with S. mansoni caused pronounced elevations in both serum TGF-β1 (P < 0.001) and MMP-2 (P < 0.01, P < 0.001) levels, 10 and 18 weeks PI respectively, when compared to their corresponding uninfected untreated groups." (PMID 22236605, 2012). "At day 9 post-infection, both control and infected wt and Mif−/− mice presented similar MMP-2 expression." (PMID 21977228, 2011). "In this study, the expression of both MMP2 and TIMP2 increased during LX-2 activation induced by TGF-β1; however, after AdNDRG2 infection, MMP2 was enhanced while TIMP2 levels decreased compared with AdLacZ controls (MMP9 and TIMP1 were undetectable)." (PMID 22110735, 2011). "In contrast, in 35 cases/43 controls carrying MMP2 C/T or T/T (associated with lower promoter activity), this protective effect was lost (AOR 1.76; 95% CI=0.06–5.2; for ever infection with HP)." (PMID 18253117, 2008). "When using several other definitions of HP infection status, the MMP2–HP interaction terms were similarly significant: MMP2 and CagA+ infection (interaction term, P=0.03), and MMP2 and current HP infection (interaction term, P=0.005)." (PMID 18253117, 2008). "However, the human osteoblast hFOB cell line secretes granulocyte-macrophage colony-stimulating factor (GM-CSF) in response to Brucella infection in a multiplicity of infection (MOI)-dependent manner which stimulates these cells to release MMP-2." (PMID 39967734, 2025). "Importantly, MMP expression associated with chlamydial infection has been shown to be sensitive to IL-17 signaling, with il17-/- mice displaying reduced oviduct expression of MMP2/MMP9 relative to wild-type mice following infection with C. muridarum." (PMID 37265500, 2023).
infection (continued). "In summary, this study demonstrated that TLR2 was required for the accumulation of mtROS after C. pneumoniae infection and highlighted the activation of JunB-Fra-1 by mtROS to promote the expression of MMP2 in the infection-induced VSMC migration and atherosclerotic lesion formation." (PMID 35493076, 2022). "Interestingly, the expression of MMP-2 was reduced in response to infections with Bsa mutants (bipB, bsaQ, chbP), OPS (oacA, wbiA, wbiD), and CPS (wcbB) mutants." (PMID 35113856, 2022). "In addition, treatment with the DP1 inhibitors S5751 and MK-0524 and L-PGDs inhibitors AT-56 and CAY10678 increased the expression of PAFR and MMP-2 during infection (P < 0.05)." (PMID 36435808, 2022). "Additionally, multiple MMPs, including MMP-2, MMP-9 and MMP-14, have been implicated in tissue pathology in the lung mucosa and female genital tract during infection through mediating inflammation and ECM degradation." (PMID 35512020, 2022). "However, MMP-2 expression following SDO mutant infection showed the same level as detected in the B. pseudomallei K96243-infected cells." (PMID 35113856, 2022). "In the liver of mice infected with E. granulosus, the expression of MMP2 is high in early post infection and decreases in the middle and late post infection, suggesting that early inflammatory cells secrete proteases including MMP2, reducing the deposition of the ECM." (PMID 31409055, 2019). "Mmp2 mRNA expression level was significantly decreased in P1-infected cells at each time point (P < 0.05) and c-myc mRNA expression was significantly decreased only at 24 h post-infection in P1-infected cells." (PMID 29593670, 2018). "Our findings on the effect of P. aeruginosa CS on 3T3L1 fibroblast cells showed that MMP-2 levels were significantly increased, which may lead to more matrix destruction and dissemination of infection." (PMID 29467483, 2018). "As immunohistochemical staining demonstrated, MMP2 and MMP9 expression in atherosclerotic lesions was substantially decreased in mice treated with Ad‐Nkx2‐5, compared to Ad‐EV‐treated controls, and Ad‐shNkx2‐5 infection significant increased the levels of MMP2 and MMP9." (PMID 27993833, 2016). "Because the expression is related to a mismatch between MMP activators and inhibitors; thus, some cells have a genotype with a greater capacity to express MMP2 when compared to others, bearing in mind that infection is a potent stimulus for metalloproteinase expression by the cholesteatomatous cell." (PMID 17505599, 2007). "DHEA treatment could not avoid the effect of cortisol on IL-6, IL-8, and MCP-1 expression but could partially avoid the inhibitory effect of cortisol on MMP-2 expression, as was demonstrated when infection experiments were performed in the presence of both cortisol and DHEA." (PMID 31695682, 2019). "In vitro studies, we found P1 infection down-regulated protein level of β-catenin and mRNA level of mmp2, prevented the β-catenin from entering into nucleus, abolished the TCF/LEF promoter activity, proved that P1 could inhibit the activation of Wnt signaling pathway in vitro." (PMID 29593670, 2018). "Mtb induces the expression of matrix metalloproteinases (MMP-2, MMP-3, and MMP-9) in the placenta, with levels varying by bacterial metabolic state and time post-infection." (PMID 41450943, 2025). "According to the results, infection of cells with CEES heightens the expression and activity of MMP-2 and MMP-9." (PMID 39359528, 2024). "To further explore the mechanisms behind PRV-induced blood-brain barrier permeability, we assessed the expression levels of MMP2, TIMP1, MMP9, and ZO-1 at various time points post-infection in bEnd.3 cells." (PMID 39436133, 2024). "Immunohistochemical staining was performed to detect the expression of matrix metalloproteinases (MMP2 and MMP9) in the brain; the expression was significantly increased from day 3 post-infection (P < 0.01)." (PMID 37452371, 2023).
infection (continued). "Especially, the gelatinases MMP-2 and MMP-9, which breakdown the extracellular matrix (ECM) components, have been displayed to be upregulated in vitro following infection with Burkholderia cenocepacia." (PMID 35113856, 2022). "Previously, there was a report of upregulation of MMP-2 and MMP-9 during the infection of host cells with B. cenocepacia." (PMID 35113856, 2022). "In both TLR4WT and TLR4mut mice, there was still a significant induction of BBB permeability, ICAM-1, MMP-2 and CCL-2 in the brains during VEEV TC-83 infection." (PMID 33487119, 2021). "In vitro studies in human astrocytic and microglial cells with human coronavirus showed an increase in the levels of MMP2 and MMP9 in infection." (PMID 32595353, 2020). "At 48 h after infection of SW480 cells with a lentiviral vector overexpressing miR-518c-5p, the expression levels of hsa_circ_0007843 and MMP2 were decreased." (PMID 32158464, 2020). "Western blot analysis revealed that the levels of p-ERK1/2, MMP-2, and MMP-9 were remarkably increased after infection with SPARC for 72 h." (PMID 32670867, 2020). "Although MMP-2 and MMP-9 were both found to be expressed at the site of infection, only in 36% of patients with M. mycetomatis the activated form of MMP-9 was present." (PMID 31295246, 2019). "Western blot analysis showed that the expression of p-FAK, p-PI3K, p-Akt, MMP-2, and MMP-9 was increased in corneal tissue at 2 days after infection and decreased from 7d to 2d, 14d, and 28d." (PMID 31061823, 2019). "Evaluation of the change in MMP14 expression compared to other invadopodia-activated MPPs, MMP2 and MMP9, showed a significant increase in expression of all three MMPs; however, MMP14 showed the highest increase in expression following infection." (PMID 31694343, 2019). "After 7 days of infection with HSV-1, the expression of MMP-2 and MMP-9 in corneal tissue was stronger than that of 0d but lower than that of 2d." (PMID 31061823, 2019). "The expression of p-Akt, MMP-2, and MMP-9 at 7 days after infection was significantly higher than that at 0 days (P< 0.05)." (PMID 31061823, 2019). "Zymography studies indicated that these proteases can activate host matrix metalloproteases (MMPs) to establish infection, through conversion of pro-MMP-2 to active MMP-2." (PMID 29467483, 2018). "Here, we assayed MMP2, MMP7, MMP9, TIMP1, and TIMP2, which have previously been described to be differentially expressed after infection of the CNS." (PMID 30442185, 2018). "Several MMPs, such as MMP-2 and MMP-9, are important in lung remodeling before and after birth as well as in response to environmental indices, infection, and lung injury." (PMID 30114253, 2018). "Endogenous mmp2, mmp7, mmp9, DKK-1, c-myc and CCND-1 mRNA and β-catenin protein expression levels were detected in P1-infected ST cells at 24, 48, and 72 h post-infection and compared with those in uninfected cells." (PMID 29593670, 2018). "Moreover, infection with shc-Jun versus scramble shRNA abolished PARP1 overexpression-induced expression of CyclinD1, Pcna, Mmp9 and Mmp2 genes, as well as the increase in the neointima/media ratio of balloon-injured arteries." (PMID 40744995, 2025). "Similarly, the protein level of Col1α1, MMP2, and α-SMA was also markedly decreased by ATF3-shRNAs infection." (PMID 33311456, 2020). "Besides, in the human infection context, some patients in the second stage of HAT (the neurological stage) present an increase in the expression of MMP-2 and MMP-9, correlated with the presence of parasites and leukocytes." (PMID 31597256, 2019). "Mmp2/9−/− mice showed higher bacterial burdens when compared to WT mice and increased levels of IL‐17, IP‐10, and RANTES in the lungs 36, similar to the observed for AIRmin mice at 48 h post‐infection." (PMID 29119707, 2018). "Likewise, matrix metallopeptidase 1 (MMP1), MMP2, and MMP14 were significantly up-regulated while the transcript of MMP11 was repressed by infection." (PMID 27197554, 2016).
infection (continued). "Further, the data suggest that absence of the E1A protein does not alter MMP2 or MMP9 activity or mRNA levels during infection." (PMID 27303733, 2016). "We found that MAV-1 infection increased MMP2 and MMP9 activity compared to mock infections." (PMID 27303733, 2016). "Similarly, we also found an up regulation of tissue remodeling factors induced by extracellular infection with WCH-SK2WT (MMP1, MMP2, and MMP10) and WCH-SK2SCV (MMP1 and MMP9) as well as intracellular infection with WCH-SK2WT (MMP9)." (PMID 28083514, 2016). "At 40 h, MMP-2 expression levels in non-infected cells was significantly different from that in the same cells at 2 and 20 h after infection (P<0.05)." (PMID 24348806, 2014). "Moreover, colonic expression of MMP-2 and TIMP-1 was similar in Lcn2+/+ and Lcn2−/− mice after infection, excluding their involvement in this process." (PMID 24465207, 2014). "Increases in MMP-2 protein expression were slower and were not significantly different from that of the normal cells 2 h after infection, but increased with time from 20 to 40 h." (PMID 24348806, 2014). "Interestingly, less distinct intestinal immunopathology was accompanied by lower colonic expression levels of the matrix-degrading enzyme MMP-2 and its endogenous inhibitor TIMP-1 seven days following ∆htrA as compared to the parental strain infection." (PMID 24883112, 2014). "In addition, MMP-2 and TGF-β1 levels continued to rise reaching the highest level at the 18th week post infection." (PMID 22236605, 2012). "MMP-2 secretion profile showed that although its concentration was increased in the AMN side with the three infection modalities, this increase was not significant." (PMID 21266053, 2011). "Infection of chorioamniotic membranes with E. coli induces an increase in the secretion of inactive forms and an association to ECM of active forms of MMP-2 and MMP-9 without changes in TIMP-1, -2, and -4." (PMID 21266053, 2011). "In this study, we demonstrated that a TNF-dependent cytokine network involving M.tb-infected monocytes, but not direct infection by M.tb, down-regulates MMP-2 secretion from microglial cells via p38 MAP kinase, NFκB and caspase 8 pathways." (PMID 21569377, 2011). "Our results are in accordance with the literature on response of IL6 family of cytokines and their importance, in addition, we find that matrix metalloproteinase 2 (MMP2) and matrix metalloproteinase 9 (MMP9) with keratan sulfate synthesis pathway may play a key role in the infection." (PMID 32595353, 2020). "However, with the crossover in cytokine and chemokine regulation by MMP2 and MMP3, it remains unclear how the effect of NRTN on the production of MMP2 and MMP3 by macrophages influences the inflammatory response to an infection in vivo." (PMID 33020210, 2020). "The present study validated the change in MMP-2 protein expression in corneal epithelial cells within 2 days of infection, indicating that MMP-2 synthesized by epithelial cells at the early stages of infection is important in the formation of corneal stromal ulcers." (PMID 24348806, 2014). "TIVE-LTC cells secreted diminished levels of MMP-2 when compared to de novo infected cells, therefore COX-2 inhibition could not effectively down-regulate active MMP-2 secretion during de novo infection compared to TIVE-LTC cells." (PMID 20169190, 2010). "In addition, we also demonstrate that an infection of VSMC with CAPN1 increases the transcription and protein expression of MT1-MMP, an activator of MMP2, and decreases protein levels of TIMP2, an inhibitor of MMP2 (Jiang LQ, unpublished data)." (PMID 18493299, 2008). "However, secretion of MMP-2 and ADAM/ADAMTS-family proteins may constitute a means by which Chlamydia reorganizes the ECM prior to this event, potentially independent of infection-associated EMT." (PMID 37265500, 2023).
infection (continued). "We observed an increase in the MMP-14 staining in the maternal stroma and caruncular epithelium of Nc-Spain1H placentomes at 10 dpi, whereas MMP-2 and TIMP-2 staining was not apparently modified by the infection (not shown)." (PMID 32552750, 2020). "By contrast, in adipocytes, no further increase of the MMP-2 and MMP-9 activity was detected for any MOI of infection." (PMID 33071987, 2020). "We observed increased expression of MMP-9, but not TIMP-1 or MMP-2, in both CHME-3 and ARPR-19 cells following infection with P. aeruginosa strains." (PMID 32423093, 2020). "The first profile includes factors that are not affected by infection, such as G-CSF, VEGF-A, MMP-2, and MMP-9 in the decidua and VEGF-A, MMP-2 in the placenta." (PMID 30420629, 2018). "Additionally, the infection prior to IS does not elevate plasma protein levels of MMP‐2, sICAM‐1, and FIX to the same extent as IS without a preceding infection." (PMID 39972966, 2025). "Furthermore, mRNA expression of both MMP2 and MMP9 in the B.suis.S2 infection group was not significantly different from the non-infected group." (PMID 26904517, 2016). "Also in mycetoma lesions both MMP-2 and MMP-9 are expressed at the site of infection, however to date there is no data indicating whether a Th17 response plays a role in the mycetoma granuloma formation and if there is a correlation between IL-17A expression and MMP expression in mycetoma lesions." (PMID 31295246, 2019).